INS (insulin)
Diseases named in the same sentence as INS in open-access papers (continued):
Sharing a sentence is not in itself a finding about the gene and the disease.
Hypoglycemia (continued). "Metabolic complications include hypoglycemia, especially when GLP-1RAs are combined with insulin or sulfonylureas, requiring careful dose adjustment." (PMID 41283270, 2025). "The accumulating literature suggests that POL has an affirmative effect on insulin sensitization and secretion, mediated by the AMPK/PI3K/Akt signaling pathways, leading to hypoglycemia." (PMID 41462653, 2025). "The most effective and reliable therapy for improving HbA1c levels, reducing hypoglycemia, and maintaining glucose within the target range is CSII, commonly known as insulin pump therapy, combined with CGM systems." (PMID 40217595, 2025). "In terms of hypoglycemia treatment, current recommendations for hypoglycemia medication for diabetics with COVID-19 mainly contain the use of metformin and DPP-4 inhibitors for mild cases and the addition of insulin for severe cases." (PMID 39944495, 2025). "In addition, while overall time below target range may be improved with HCL system use, suboptimal carbohydrate/insulin matching can lead to glycemic excursions characterized by rising blood glucoses followed by temporary rebound hypoglycemia from resultant automated delivery of high insulin doses." (PMID 39933614, 2025). "However, the use of insulin in non-diabetic patients carries a risk of hypoglycemia, and the long-term use of heparin may lead to overconsumption of lipoprotein lipase." (PMID 40101052, 2025). "Biochemical investigations for the hypoglycemia reconfirmed CHI with a blood glucose level of 2.6 mmol/L (47 mg/d), insulin 127 pmol/L (18.2 μU/mL), and ketones 0.1 mmol/L." (PMID 40492016, 2025). "Despite receiving intensive insulin therapy (IIT), she experienced severe glycemic fluctuations (38-361 mg/dL; mean±SD: 218.6±110.0 mg/dL) and recurrent hypoglycemia, rendering oral intake nearly impossible." (PMID 39931500, 2025). "Compared to the insulin sliding scale (ISS), the IIT group required correction for hypoglycemia at a rate of 2.77% (p = 0.38), down from 6.8%." (PMID 41426511, 2025). "This systematic review aims to synthesize evidence on the efficacy and safety of different fluid and insulin strategies in managing DKA and hypoglycemia in diverse patient populations." (PMID 41262789, 2025). "The study revealed that both the insulin pump and MDI groups experienced significant and enduring reductions in HbA1c levels and rates of severe hypoglycemia, clinically significant outcomes." (PMID 41146752, 2025). "The strong signals were hypoglycaemia (IC025 = 4.26), shock hypoglycaemic (IC025 = 3.68), hypoglycaemia unawareness (IC025 = 3.30), insulin resistance (IC025 = 3.02) and dawn phenomenon (IC025 = 3.01)." (PMID 40997126, 2025). "Many insulin pens can be connected with CGM systems to further improve insulin therapy by supporting adherence with MDI, with enhanced safety by minimising hypoglycaemia." (PMID 41039947, 2025). "This mismatch between insulin bioavailability and blood glucose levels is central to the pathogenesis of IAS-induced hypoglycemia." (PMID 40648766, 2025). "EIAS is a condition characterized by a clear history of exogenous insulin administration, in the absence of exposure to sulfhydryl-containing drugs or underlying autoimmune diseases, and with exclusion of insulinoma, type B insulin resistance, and other causes of hypoglycemia." (PMID 41585798, 2025). "Glibenclamide was found to be inferior to both insulin and metformin, regarding maternal weight gain, LGA, macrosomia and neonatal hypoglycemia." (PMID 40235646, 2025). "The findings of this systematic review provide a comprehensive synthesis of the comparative effectiveness of intravenous fluids and insulin regimens in the acute management of DKA and hypoglycemia." (PMID 41262789, 2025). "The clinical relevance of avexitide’s GLP-1R antagonism is underscored by its therapeutic use in treating postbariatric hypoglycemia (PBH), a condition characterized by excessive insulin secretion following gastric bypass surgery." (PMID 41226200, 2025).
Hypoglycemia (continued). "This systematic review suggests the safety and efficacy of lower insulin doses in mild-to-moderate pediatric DKA, with significant reductions in hypoglycemia and hypokalemia." (PMID 41227190, 2025). "Fear of hypoglycemia (FoH) is a common phenomenon in T1DM, contributing to poor glycemic control and, at times, maladaptive behaviors such as insulin underuse or excessive correction of perceived lows." (PMID 40630348, 2025). "Multivariable logistic regression analysis indicated that knowledge of insulin self-administration, specifically a low level of knowledge (AOR=4.87; 95% CI: 1.55-15.26), was a predictor variable for self-reported hypoglycemia." (PMID 40110390, 2025). "Hypoglycemia is further exacerbated by IGF-2 binding to IGF-1R and IR at the pancreatic alpha cells and hypothalamus, which mimics the effects of insulin and IGF-1 to suppress secretion of counterregulatory hormones—glucagon and GH." (PMID 41179270, 2025). "This systematic review aims to comprehensively evaluate and compare the effectiveness of different intravenous fluid regimens and insulin protocols employed in the acute management of DKA and hypoglycemia." (PMID 41262789, 2025). "A monitored 72-hour fasting test revealed hypoglycemia (capillary blood glucose (CBG) 42 mg/dL), suppressed insulin (<0.20 μIU/mL), and C-peptide (0.12 ng/mL), thereby excluding insulinoma and factitious hypoglycemia." (PMID 41333493, 2025). "This case highlights the benefits of insulin pump therapy in elderly patients with T1DM and multiple comorbidities, demonstrating its potential to enhance glycemic control, reduce hypoglycemia, and improve overall quality of life." (PMID 41473654, 2025). "Serum samples drawn prior to hypoglycemia correction revealed an elevated IGF-2:IGF-1 ratio of 60.7 (normal <10) with low paired C-peptide and insulin, consistent with an IGF-2–secreting tumor." (PMID 40270996, 2025). "The earlier AID system included insulin pumps with automated suspension of insulin delivery at low glucose levels (low glucose suspend, LGS) or for predictive hypoglycemia (predictive low glucose suspend, PLGS)." (PMID 40565985, 2025). "In addition, long-term insulin use may lead to complications such as hypoglycemia." (PMID 40796840, 2025). "Glycemic variables included mean glucose, time in range (TIR), time below range (TBR), time in level 2 hypoglycemia, time above range (TAR), time > 250 mg/dL, and total daily insulin dose." (PMID 41026404, 2025). "The data allow side-by-side comparison of different insulin regimens, fluid therapies, and dextrose concentrations used for managing DKA and hypoglycemia." (PMID 41262789, 2025). "Participants announced PA at least 30 min before exercise, which reduced insulin delivery, and, if necessary, a certain amount of CHO was also recommended by the system to avoid hypoglycaemia." (PMID 39653802, 2025). "Their structured approach can mitigate risks like hypoglycemia or DKA when patients transition to lower-carb patterns, particularly if insulin-to-carb ratios change dramatically." (PMID 40573112, 2025). "Initiation of long-acting insulin among insulin-naïve patients on OHD failure improved glycemic control and reduced HbA1c levels, while mitigating hypoglycemia events." (PMID 40303934, 2025). "Asymptomatic hypoglycemia was detected in four dogs receiving DWP16001, but it resolved following insulin dose adjustment." (PMID 40796840, 2025). "Any occurrence of hypoglycemia can lead to catastrophic effects, and it can occur in the acute management of DKA with continuous infusion of insulin therapy." (PMID 41458864, 2025). "We constructed an evidence map that arrays dietary intervention types on the X-axis and main outcome categories (HbA1c, insulin dose, glycemic variability, TIR, lipids, weight/BMI, diet quality/adherence, QoL, and safety—hypoglycemia) on the Y-axis." (PMID 41228423, 2025).
Hypoglycemia (continued). "Low-dose insulin (0.05 unit/kg/hour) in pediatric DKA showed comparable efficacy to the standard dose (0.1 unit/kg/hour), with fewer hypoglycemia (3.3% vs. 13.3%) and hypokalemia events (30% vs. 43.3%)." (PMID 41262789, 2025). "The systematic review included nine studies examining the comparative effectiveness of intravenous fluids and insulin regimens in the acute management of DKA and hypoglycemia." (PMID 41262789, 2025). "Older meta‐analyses (2012) demonstrated that overall, insulin pumps and MDI had comparable outcomes in relation to glycaemic control and hypoglycaemia." (PMID 40390300, 2025). "But hypoglycaemia is usual in T1DM too, reflecting the inadequacy of our current insulin delivery after >100 years of attempts to do better." (PMID 40035222, 2025). "RCTs with a duration of ≥ 4 weeks were deemed eligible for the incidence of severe hypoglycemia, time-in-range (TIR), total insulin dose (TID), change in C-peptide, and glucagon levels." (PMID 40760325, 2025). "HI is diagnosed by demonstration of increased insulin secretion and actions during hypoglycemia, including detectable insulin, low free fatty acids (FFAs) and beta-hydroxybutyrate (BOHB), and a glycemic response to glucagon administration during hypoglycemia." (PMID 39483531, 2024). "Severe hypoglycemia (SH) and diabetic ketoacidosis (DKA) remain significant risks with intensive insulin therapy." (PMID 37782904, 2024). "Recurrent hypoglycemia occurred in 3 of 13 patients treated with insulin after SVR (23%), and the insulin dose was reduced in these patients." (PMID 38709148, 2024). "If glycemic control remains inadequate, changing the type of insulin or using medications like alpha-glucosidase inhibitors, DPP-4 inhibitors, and GLP-1RA can help lower blood glucose levels while preventing hypoglycemia." (PMID 39575003, 2024). "Their QOL and FOH were evaluated with Insulin Therapy Related Quality of Life Measure Questionnaire-Chinese version (ITR-QOL-CV) and the Chinese Version Hypoglycemia Fear Survey-Worry Scale (CHFSII-WS), and their HbA1C were collected at the same time." (PMID 38872219, 2024). "However, recurrent hypoglycaemic states such as in HAAF diminishes the adrenaline response (as will be discussed later in this review), thus recurrent hypoglycaemia may diminish cortisol release, ultimately impacting the control of insulin release from the pancreas." (PMID 38392992, 2024). "As T1DM is insulin-dependent, hypoglycemia is a more pervasive problem for these patients; therefore, patients with T1DM are more prone to the consequences of hypoglycemia." (PMID 39539431, 2024). "In this study, we establish a rodent model of T2D, characterize the counterregulatory response to hypoglycemia and evaluate proof of concept and efficacy of the SSTR2 antagonists PRL-2903 and ZT-01 to prevent insulin-induced hypoglycemia." (PMID 38510652, 2024). "To capture the characteristics of patients with hypoglycemia, we compared the results of the OGTT, insulin resistance test, insulin secretory capacity, and HbA1c levels, but no apparent differences were observed." (PMID 39274465, 2024). "Meanwhile, insulin degludec and glargine contributed to better HbA1c and TIR with reduced hypoglycemia in toddlers and preschoolers with T1DM." (PMID 39075573, 2024). "Dual-hormone CLS delivering insulin and glucagon or insulin and the amylin analogue, pramlintide, aim to more closely imitate pancreatic glucose control physiology and may improve performance with regards to managing postprandial glucose excursions and exercise-induced hypoglycemia." (PMID 39390689, 2024). "However, sporadic glucose monitoring and poor patient adherence, driven by a multitude of factors, including pain and the tediousness of procedures, often lead to unpredictable insulin dosages, which could result in uncontrolled hyperglycemia, hypoglycemia, seizures, unconsciousness, or death." (PMID 39000136, 2024).
Hypoglycemia (continued). "The cost savings from preventing severe hypoglycaemia episodes were RM4,377 for insulin glargine and RM12,753 for insulin detemir." (PMID 38694591, 2024). "In addition, as previously discussed, TIR data from 2 icodec phase 3studies at the time of the switch from once-daily basal insulin to icodec showed thatsuch switches did not lead to a loss of glycemic control or more hypoglycemia when aloading dose was administered." (PMID 38224978, 2024). "When insulin is absorbed relatively quickly by NFI, patients need to be more vigilant about hypoglycemia." (PMID 38803476, 2024). "Isolated islets from G6PC2−/− mice exhibit a left shift in GSIS, such that under fasting conditions, insulin levels are the same as wild-type mice, inferring G6PC2’s potential role in protecting against hypoglycemia under stressed conditions." (PMID 38731997, 2024). "In NICTH, big IGF-2 forms a complex that is biologically active and saturates the insulin and IGF receptors, resulting in refractory hypoglycemia." (PMID 38405103, 2024). "Although a discrepancy between blood insulin and C-peptide levels points to insulin analog intake, IAS should also be considered, particularly in a patient with transient hypoglycemia." (PMID 39071705, 2024). "In response to strong allostatic challenges, such as hypoglycemia, the CNS coordinates the CRR to promote glucagon release and suppress insulin secretion, which augments glycogenolysis and gluconeogenic capacity." (PMID 38826340, 2024). "This study aims to compare the glycated hemoglobin (HbA1C), insulin therapy related quality of life (ITR-QOL), fear of hypoglycemia (FOH) of adult T1DM patients treated with MDI and CSII based on propensity score matching in real-world conditions in China." (PMID 38872219, 2024). "The presumed mechanism of hypoglycemia in IAS is a mismatch between the glucose level and the free insulin concentration, resulting from the formation of insulin-IAA complexes after insulin is released postprandially." (PMID 39119412, 2024). "A few retrospective studies have reported varying degrees of GC and hypoglycemia rates in patients treated with different insulin regimens, including once-daily glargine, twice-daily NPH, every six hours NPH, biphasic insulin, and SSRI." (PMID 39203739, 2024). "Treatment with metformin, insulin or GLP-1 receptor agonists has been used with variable effects on glucose control, with reports of hypoglycaemia." (PMID 39595809, 2024). "Our findings, adjusted for total daily insulin use, suggest an optimal amount of carbohydrate intake that is low enough to increase TIR but high enough to prevent hypoglycaemia." (PMID 38967668, 2024). "Insulin delivery method, glucose monitoring method, HbA1c, mean glucose concentration, number of glucose measurements, insulin dosing, carbohydrate consumption, DKA episodes requiring hospitalization, and severe hypoglycemia episodes requiring hospitalization." (PMID 39867016, 2024). "Big IGF-II has increased bioactivity to induce insulin signaling compared with mature IGF-II, resulting in spontaneous hypoglycemia." (PMID 39689018, 2024). "One of them presented an episode of hypoglycemia after the initiation of SGLT-2 inhibitors concomitant with the previously prescribed hypoglycemic treatment (GLP-1ra and insulin) and the other patient had repeated episodes of UTI." (PMID 39202480, 2024). "However, insulin could lead to side effects such as weight gain and hypoglycemia." (PMID 38803476, 2024). "The issue of hypoglycemia has been controversial, with some studies showing the advantage of long‐acting insulin in reducing hypoglycemia episodes compared with NPH,34, 35 whereas in others, the rates of hypoglycemia were comparable." (PMID 38664886, 2024). "At 18 weeks post-TPIAT, she began experiencing episodes of symptomatic postprandial hypoglycemia as low as 2.5 mmol/L on her CGM, several hours following her last dose of insulin aspart." (PMID 39450137, 2024).
Hypoglycemia (continued). "Consequently, metformin reduces insulin sensitivity without causing weight gain or hypoglycemia." (PMID 39336874, 2024). "The patient presented with severe hypoglycemia and a history of multiple admissions for diabetes ketoacidosis (DKA) despite insulin therapy." (PMID 39156415, 2024). "Of the 163 patients who received insulin during the LSITP, 86 (52.7%) developed hypoglycemia during this phase." (PMID 38594758, 2024). "The differential diagnosis in patients with endogenous insulin-mediated hypoglycemia includes insulinoma, NIPHS, oral hypoglycemic agent-induced hypoglycemia, and insulin autoimmune hypoglycemia." (PMID 39125476, 2024). "Patients who had hypoglycemia during the IIITP had lower BMI, lower frequency of hyperkalemia, higher intravenous insulin doses in the first 24 h of admission, and longer IIITP duration." (PMID 38594758, 2024). "Hypoglycemia is most commonly recognized 1–3 hours after meals, potentially related to the even greater increases in meal-stimulated GLP-1 and insulin secretion in patients with PBH as compared with unaffected post-surgical patients." (PMID 39264731, 2024). "Insulin administration is also associated with decreased glucose utilization in the LC, but evidence indicates that this may be a direct effect of insulin itself and not the hypoglycemia produced by insulin." (PMID 37048567, 2023). "In insulin-treated persons with T1D, low levels of blood glucose (hypoglycemia) is a dreaded acute complication, which in mild forms leads to symptoms such as fatigue, trembling or hunger, whereas episodes of nocturnal hypoglycemia are mostly unrecognized and therefore may persist for hours." (PMID 38155742, 2023). "Conversely, exogenous insulin can induce autoimmune syndrome (EIAS), which mainly manifests as hyperinsulinemia and unexpected hypoglycemia." (PMID 37324170, 2023). "Weight gain in patients with T1D is related to insulin therapy, especially intensive (IIT), and a tendency to low physical activity for fear of hypoglycemia as well as increased consumption of simple carbohydrates before or during exercise." (PMID 37065759, 2023). "This study investigated users’ experiences with the Hypo-METRICS smartphone app, a tool developed for research purposes to explore the impact of hypoglycemia on daily functioning in real life among people with T1DM and insulin-treated T2DM." (PMID 37773626, 2023). "Furthermore, East African patients may not have the availability of insulin analogues which are thought to help reduce glycemic variability and risk of hypoglycemia." (PMID 38706529, 2023). "Moreover, the tumor might secrete insulin, therefore inducing hypoglycemia." (PMID 37238376, 2023). "Large reductions in basal circulating insulin and complete inhibition of nutrient-stimulated insulin secretion observed in IUGR fetal sheep were the direct result of fetal hypoxemia and hypoglycemia." (PMID 37727657, 2023). "In this study, the postoperative incidence rate of hypoglycemia in T2DM patients (24.78%) was slightly higher than previous studies, possibly due to the use of insulin after surgery." (PMID 37675290, 2023). "Apart from its insulin-stimulating effects, GIP, during hypoglycemia, stimulates glucagon secretion, enhances the absorption of fatty acids in adipocytes, increases the deposition of triglycerides in subcutaneous adipose tissue and decreases bone reabsorption." (PMID 37927592, 2023). "A lower rate of nocturnal symptomatic hypoglycemia was found during treatment with insulin degludec compared to insulin glargine U100, with an RRR of 28% for level 1 hypoglycemia (p < 0.05) and 37% for level 2 hypoglycemia (p < 0.005)." (PMID 38089060, 2023). "Surprisingly, however, TFEB/TFE3‐deficient mice, despite showing a massive increase in INS mRNA levels, do not show hypoglycemia but instead are glucose intolerant, suggesting that lack of TFEB and TFE3 may affect β‐cell function and insulin production at different levels." (PMID 37712288, 2023).